TNF (tumor necrosis factor)
Diseases named in the same sentence as TNF in open-access papers (continued):
Sharing a sentence is not in itself a finding about the gene and the disease.
heart failure (continued). "However, the protective role of TNF-α in heart failure models remains unclear." (PMID 32426037, 2020). "Pro-inflammatory cytokines including tumor necrosis factor-α (TNF-α), interferon gamma (IFN-γ) and interleukin-6 (IL-6) appear to make a significant contribution to the pathophysiology of cardiomyopathy and heart failure." (PMID 31998452, 2019). "For a long time, the well-known cytokine tumor necrosis factor-alpha (TNF-α) was held accountable for myocardial dysfunction in events where hypoxia was established for enough time, notably in IRI or heart failure." (PMID 31614478, 2019). "Our findings that rats with decompensated CHF display lower levels of immunoreactive TNF-α as compared with sham-operated rats and even compensated CHF animals is in contrary to the clinical findings where TNF-α levels are increased in heart failure." (PMID 29774097, 2018). "TNF-α inhibition therapy was examined in large clinical trials with heart failure patients, using TNF-α antagonist infliximab or TNF-α antibody etanercept." (PMID 28460644, 2017). "Then we took Angiotensin II Receptor (Type 1) (AGTR1), TNF-α and Heme oxygenase 1 (HMOX1) as an example to explain the potential synergistic mechanism of active components in SND for curing heart failure." (PMID 27095146, 2016). "Elevated levels of biomarkers involving systemic inflammation, immune function, and ventricular remodeling, including AST, LDH, CRP, CK, HBDH, TNF-α, ET-1, ICAM-1, and MCP-1, also have been related to morbidity and mortality among heart failure patients." (PMID 26269254, 2015). "We measured pleural fluid levels of TNF-α and MMPs in patients with TBP (n = 18) or heart failure (n = 18) as controls." (PMID 26367274, 2015). "Circulating TNFα and its two receptors (TNFR1 and TNFR2) are elevated in patients with heart failure relative to controls." (PMID 24923671, 2014). "TNF-α can induce activation of NAD(P)H oxidase leading to enhance oxidative stress and mediate NAD(P)H oxidase-derived superoxide production during heart failure." (PMID 25984330, 2014). "In heart failure, administration of MSC post infarct has been demonstrated to decrease production of TNF-alpha and IL-6, but upregulate generation of the anti-inflammatory cytokine IL-10, which correlated with therapeutic benefit." (PMID 20398245, 2010). "The pro-inflammatory cytokine tumor necrosis factor-alpha (TNF) and the cleaved extracellular domain of its type-1 receptor (sTNFR1) are recognized biomarkers of heart failure severity and adverse outcomes of the disease." (PMID 19319187, 2009). "TNFα is increased in serum of patients with CHF and correlates with the severity of heart failure, cachexia, and clinical outcome." (PMID 20224758, 2009). "Disappointing results may stem from the complex, dual role of TNF-α via TNFR1 (inflammation/apoptosis) and TNFR2 (repair/survival), and the multifactorial nature of heart failure." (PMID 41011058, 2025). "The publication bias test was performed using the Begg test which shows that the P value of each outcome indicator was greater than 0.05 (heart failure markers: P = 0.061, CRP: P = 0.602, TNF-α: P = 0.317, and IL-6: P = 0.317), and therefore the possibility of publication bias was low." (PMID 41179565, 2025). "Similarly, TNF-a and IL-8 levels were found to be elevated in RHD patients with heart failure when compared to ARF patients." (PMID 41305420, 2025). "Moreover, furin and its substrates, including tumornecrosis factor-α (TNF-α), endothelin-1 (ET-1), and transforminggrowth factor-β1 (TGF-β1), are capable of mediating inflammation,hypertrophy, and fibrosis in MI and heart failure." (PMID 38481703, 2024). "Factors such as exposure duration, cytokine concentration, and model dependency must be considered, as evidenced by the contradictory effects of TNF-α observed post-myocardial infarction and in heart failure cases in humans and non-human models." (PMID 39201339, 2024).
heart failure (continued). "Based on the data, the important variables associated with the occurrence of NOAF were selected: age, CAD, heart failure, WBC, neutrophils, neutrophil percentage, CRP, PCT, TNF-α, MPO, HOCl, CR, TNI, NT-proBNP, LDL-c, SOFA score, APACHE II score, LVEF, and LVFS." (PMID 39030470, 2024). "Different mineralocorticoids such as aldosterone, as well as various inflammatory cytokines such as the tumor necrosis factor (TNF-α), the levels of which are increased in heart failure, have been reported to reduce Na+-K+ ATPase expression as well as activity and produce cardiac fibrosis." (PMID 39409137, 2024). "Previous studies on cytokines in heart failure have mainly focused on various inflammatory cytokines, such as Interleukin (IL), Interferon (IFN), Tumor Necrosis Factor superfamily (TNF), Colony Stimulating Factor (CSF), Chemokine Family, and Growth Factor (GF)." (PMID 39726944, 2024). "Treatment of myocarditis in AOSD has two arms, i.e., non-specific management of heart failure, and disease-specific treatment with corticosteroids, IL-1/IL-6 antagonists, or TNF inhibitors." (PMID 38883113, 2024). "In the cardiovascular system, TNF-α-activated signal transduction pathways play a crucial role in vascular dysfunction, CAD development and progression, and adverse cardiac remodeling following myocardial infarction and heart failure." (PMID 39684812, 2024). "Furthermore, it was found that people with CF had increased levels of interleukin-6 (IL-6) and tumor necrosis factor alpha (TNF-a), which were involved in the development of atherosclerotic plaque and heart failure." (PMID 36678185, 2023). "At present, some traditional Chinese medicines, such as Qiliqiangxin (QL), were reported to stabilize the gut microbiota after heart failure, inhibiting myocardial fibrosis and cardiac remodeling by reducing the generation of inflammatory factors, such as NLRP3, IL-1B, and TNF-α." (PMID 36771313, 2023). "The use of anti-TNF-α agents is not recommended by the New York Heart Association (NYHA) for patients with class III and IV heart failure." (PMID 37248486, 2023). "The strongest keywords were “coronary heart disease (20.73),” and most recently “heart failure (18.28), nonsteroidal anti-inflammatory drug (NSAIDs) (17.51), oxidative stress (16.62), c reactive protein (12.18), and tumor necrosis factor (10.36)." (PMID 36873405, 2023). "Proinflammatory cytokines such as TNF-α and IL-6, acting directly on the myocardium at a later stage of DOX-induced cardiac injury, generate additional oxidative/nitrosative stress with hypertrophy and fibrosis, ultimately leading to heart failure." (PMID 37242448, 2023). "The strongest keywords were “coronary heart disease (20.73),” and most recently “heart failure (18.28),” nonsteroidal anti-inflammatory drug (17.51), oxidative stress (16.62), c reactive protein (12.18), tumor necrosis factor (10.36)." (PMID 36873405, 2023). "Overall, the data indicate that treatment with SCoV2-epitope leads to an increase in the secretion of proinflammatory cytokine GM-CSF while decreasing the secretion of TNF-α, IL-6, and CCL2, which can contribute to the damage of primary cardiomyocytes and potentially lead to cardiac failure." (PMID 38068877, 2023). "In summary, TSP-1 might not only be related to plaque formation but also play an essential role in heart failure and may also have a mechanistic connection with TSP-1 expression in promoting the release of tumor necrosis factor-alpha (TNF-α) from macrophages." (PMID 38145212, 2023). "Atrial natriuretic peptide (ANP) and tumor necrosis factor-α (TNF-α) were removed during PD treatment in heart failure despite no improvement in renal function." (PMID 37374112, 2023).
heart failure (continued). "After classification of the AF patients into PAF and PeAF patients, we observed a high heart failure (HF) rate, increased levels of LAD, elevated serum concentrations of BNP, MDA, TNF-α, IL-6, CTX-I, TGF-β1, and lower expression of SOD (P<0.05) in PeAF patients than in PAF patients." (PMID 37275755, 2023). "In the group of inflammatory biomarkers of heart failure are some traditional biomarkers, such as C-reactive protein (CRP) and high-sensitivity C-reactive protein (hs-CRP), tumor necrosis factor-alpha (TNF-α), interleukin-6 (IL-6), as well as some new biomarkers." (PMID 35626917, 2022). "In addition, TNF-α blockers cannot show efficacy in diseases where TNF-α acts as a disease-promoting factor, including multiple sclerosis and heart failure." (PMID 35955688, 2022). "Recent studies have shown that the expression of TNF-α and IL-6 genes increases in CHF patients, and are positively correlated with the severity of heart failure, thus indicating that the expression of pro-inflammatory cytokines is a significant factor in the severity of CHF." (PMID 35734399, 2022). "Anthracyclines also activate pro-inflammatory pathways involving nuclear factor-kB (NF-kB) and tumor necrosis factor alpha (TNF-α) and upregulate the transcription of NLRP3, interleukin (IL)-1β and IL-6, key inflammatory mediators of heart failure pathogenesis." (PMID 35528842, 2022). "In addition, TNF-α blockers cannot show efficacy in diseases where TNF-α acts as the disease-promoting factor, including multiple sclerosis and heart failure." (PMID 35202182, 2022). "Additionally, a correlation was observed between the concentration of TNF- α, the level of NT-proBNP, and the NYHA heart failure class." (PMID 35269577, 2022). "Although circulating and cardiac TNF-α concentrations are lower in healthy individuals, higher TNF-α concentrations alter myocardial function, primarily in ischemia/reperfusion, remodeling, and heart failure." (PMID 36091399, 2022). "Anti-TNF-α treatments investigated in animal models of heart failure showed great promise; unfortunately, these hopes have not been fulfilled in clinical studies." (PMID 35309046, 2022). "Another study reported that etanercept and infliximab (5 and 10 mg/kg) do not improve cardiac function; therefore, anti-TNF drugs are not recommended for patients with heart failure." (PMID 35187113, 2021). "Despite the body of experimental and clinical evidence, there are limitations in the role of anti-TNF-α therapy as its clinical benefit has not been demonstrated in heart failure." (PMID 34071276, 2021). "Furthermore, levels of IL-6, TNF-α and adiponectin increased according to NYHA class and correlated with all heart failure severity parameters (LVEF, mPAP, PCWP, and BNP), except TNF-α, which did not correlate with PCWP." (PMID 34685378, 2021). "This could trigger the production of pro-inflammatory mediators, such as IL1, IL6, TNF-α, and TGF-β, contributing to cardiac remodeling and heart failure." (PMID 34884782, 2021). "Additionally, our results supplement and consolidate previous findings, in which, besides having an association with NYHA and BNP, cytokines also correlated with other heart failure severity parameters, such as LVEF, PCWP (except TNF-α), and mPAP." (PMID 34685378, 2021). "ERBB3 mRNA expression levels on the surface of monocytes were reported to be inversely correlated with tumor necrosis factor alpha in subjects with heart failure but not in human subjects without heart failure." (PMID 34176482, 2021). "In DOX-induced heart failure mice, SOD2, GPx-1, FOX3a, and SIRT3 expression are decreased, apoptotic cells and cleaved-caspase-3 expression are increased, as well as inflammatory cytokines such as IL-1β, IL-6, and TNF-α are increased." (PMID 34513812, 2021).
heart failure (continued). "Congestive heart failure: Although some clinical trials showed worse prognosis with increasing the TNF-α blockers, the overall conclusion showed no need to screen for heart failure with echo unless the patient has a history of heart failure." (PMID 33209528, 2020). "Given the evidence that the pro-inflammatory cytokine TNFα and soluble TNF receptors correlate with mortality in heart failure, it is thought that targeting this mediator may be beneficial in stopping heart failure deterioration." (PMID 33344515, 2020). "Tumor necrosis factor-alpha (TNF-α) plays an important pathogenic role in cardiac hypertrophy and heart failure (HF); however, anti-TNF is paradoxically negative in clinical trials and even worsens HF, indicating a possible protective role of TNF-α in HF." (PMID 33270628, 2020). "Moreover, as an inflammatory response factor, tumor necrosis factor α (TNF-α) levels ≥1.0 ng/ml can inhibit myocardial contraction and be an indicator of heart failure severity." (PMID 32655670, 2020). "Given the lack of benefit in patients with heart failure, as well as the potential for TNF-α inhibitors to adversely affect lipid profiles, interest in targeting TNF-α in atherosclerotic CVD has been limited." (PMID 31357404, 2019). "It was reported that normal heart does not express TNF but failing heart procures robust amount of TNF-α, Hence, more studies are dedicated to understanding the role of TNF-α in heart failure patients." (PMID 29487525, 2018). "The source of TNF in CHF is still a matter of debate and there are several hypotheses pointing to different sources of TNF in various forms of heart failure." (PMID 29895751, 2018). "Studies on animal models have shown the harmful effect of the negative inotropic effect of TNF-α on heart failure patients, in whom no transplant was performed." (PMID 29487525, 2018). "Also included in this group, tumor necrosis factor (TNF)-α and interleukin (IL)-6, key inflammatory cytokines involving in the progression of CVD and heart failure, can be upregulated by a number of uremic toxins." (PMID 30200452, 2018). "Based on the disappointing results from anti-TNF trials, the TWEAK/Fn14 axis may represent new targets for heart failure therapies." (PMID 24611063, 2014). "TNF-α trials too have so far failed to meet the expectation of cardiologist for heart failure treatment." (PMID 25324965, 2014). "In this review, we will explore the role of other members of the TNF/TNF receptor superfamily (TNFSF/TNFRSF) in cardiovascular diseases (CVDs) focusing on TWEAK and its receptor Fn14, new players in myocardial remodeling and heart failure." (PMID 24611063, 2014). "The concentrations of TNF-α and INF-γ were reported to be raised in patients with heart failure." (PMID 25214716, 2014). "Synthesis of ADAMTS4 and versican in cardiac cells was induced in vitro by TNF-α and IL-1β, cytokines found in enhanced levels in the failing myocardium, suggesting inflammation as a trigger for ADAMTS-mediated versican fragmentation in heart failure." (PMID 24595230, 2014). "During recent years, evidence has accumulated that other members of the TNFRSF/TNFSF than TNFα/TNFR might play important roles in the development and progression of heart failure as they are regulated in both experimental and clinical heart failure." (PMID 24611063, 2014). "Increased levels of PICs, such as tumor necrosis factor-alpha (TNF-α) and interleukin (IL)-6, were identified in the hypothalamic paraventricular nucleus (PVN) and other autonomic brain areas of hypertensive and heart failure rats." (PMID 24788542, 2014). "Considering that IFN-γ has antifibrotic properties and TNF-α is involved in fibrosis, the synergistic effect of the two cytokines on NOS2 expression may have contributed to the development of heart failure." (PMID 22811738, 2012). "Surprisingly, anti-TNF-α therapy had no benefit or even had harmful effects in patients with heart failure." (PMID 21949832, 2011).
heart failure (continued). "In heart failure, TNF-α transcription can be activated by NF-κB, and NF-κB itself is also dominantly regulated by TNF-α, as the increased expression of TNF-α triggers NF-κB translocation to the nucleus where it activates transcription of many inflammatory and immune response target genes." (PMID 19210763, 2009). "Evidence of the effect of anti-TNFα therapy on heart failure in RA patients without preexisting heart failure is currently very limited." (PMID 17763428, 2007). "However, the previous optimism for Tumor Necrosis Factor-Alpha (TNF-α) targeted therapy, which ultimately failed, suggests that some cytokine-based approaches may have limited roles in the treatment of heart failure." (PMID 39726944, 2024). "Indeed, TNF blockade fails or even exacerbates disease activity in TNF-driven pathologies, such as MS or heart failure, and significant patient numbers do not respond in approved applications where TNF blockers demonstrated high clinical efficacy 4,5." (PMID 38169605, 2024). "However, the Clinical trial with anti-TNFα alone did not reduce heart failure possibilities in heart failure patients and has been attributed to the counterplay of TNF receptor, TNFR1, and TNFR2 mediated inflammasome activation." (PMID 38216681, 2024). "An uncontrolled production of proinflammatory mediators, such as IL-6, IL-1β, IFN-γ, and TNF-α, drives hyperinflammation during severe COVID-19 infection, leading to cardiovascular and respiratory complications, including ARDS, disseminated intravascular coagulation, and heart failure." (PMID 35955801, 2022). "A critical role of the pro-inflammatory cytokine, TNF-α, in the SFO is further reinforced by the finding that the knockdown of the TNF-α receptor 1 in the SFO reduced the increase in sympathetic nerve activity normally observed in the myocardial infarction-induced model of heart failure." (PMID 35309046, 2022). "Therefore, the existing evidence is not sufficient to conclude that TNF-α inhibitors would accelerate or worsen heart failure in ICI-induced myocarditis." (PMID 35844550, 2022). "Similarly, in the Phase III ATTACH trial of another TNF-α antibody, infliximab, the percentage of death and heart failure-related hospitalization were not improved, although plasma levels of C-reactive protein (CRP) and IL-6 decreased after each injection." (PMID 35844550, 2022). "Although TNF concentrations increase in patients with heart failure, and might contribute to cardiac cachexia, studies that have targeted TNF-α have not shown benefit in heart failure." (PMID 33924019, 2021). "However, anti-TNF treatment with the soluble TNF receptor (TNFR) etanercept, or with infliximab, a neutralizing TNF antibody, have been unsuccessful in clinical trials and have shown a worsening of heart failure in some cases." (PMID 33330676, 2020). "For example, treatment with tumor necrosis factor alpha (TNF-α) neutralizing drugs (Infliximab and Etanercept) had no beneficial effects on heart failure hospitalization or mortality, and treatment with high doses of Infliximab even caused adverse clinical outcomes." (PMID 33296366, 2020). "In case of heart failure, clinical data indicated that TNF-α inhibitors were not effective and even could worsen disease outcomes." (PMID 33053859, 2020). "Despite the fact that the SuH mice did not develop severe heart failure, we decided to evaluate the expression of markers for RV cell apoptosis (active caspase-3), exacerbated RV tissue injury and/or inflammation (TNF-α), and RV abnormal cell proliferation (p-38 MAPK and ERK5)." (PMID 30574088, 2018). "However, anti-TNF-α clinical trials using TNF-α antagonist or TNF-α antibody showed no benefit to patients with heart failure." (PMID 28460644, 2017).